TTN (titin)
Diseases named in the same sentence as TTN in open-access papers (continued):
Sharing a sentence is not in itself a finding about the gene and the disease.
cardiac hypertrophy (18 papers, 2008 to 2025). "Enriched functions in females with the Met allele included cardiac hypertrophy in response to stress, with down-regulation of the gene encoding titin (Tcap) and upregulation of BNP (Nppb), in line with altered cardiac functional parameters." (PMID 34210092, 2021). "The mechanisms by which TTN variants contribute to cardiac hypertrophy is controversial." (PMID 34445638, 2021). "Both FHL1 and FHL2 have not only been linked to cardiac hypertrophy signaling but also bind titin." (PMID 27889803, 2016). "Serum titin may be an underlying factor for cardiac hypertrophy in cats." (PMID 39619937, 2024). "Specifically, this study demonstrated that, similar to humans, alterations in titin levels in cats correlate with pathological changes such as myocardial hypertrophy and DCM." (PMID 39619937, 2024). "The titin fragment is a well-known marker of pathological cardiovascular events, such as cardiac hypertrophy and myocardial infarction, in humans." (PMID 39619937, 2024). "Focusing on the cardiovascular system, titin was found to be an acceptable prognostic biomarker for detecting pathologic cardiovascular conditions such as cardiac hypertrophy, DCM, and myocardial infarction in human patients." (PMID 39619937, 2024). "In humans, titin has been extensively studied as a biomarker of cardiovascular conditions, such as cardiac hypertrophy, DCM, and myocardial infarction." (PMID 39619937, 2024). "Endothelial cells also have an important role in paracrine signaling to the cardiomyocyte through cyclic guanosine monophosphate activation and regulating titin hyperphosphorylation and subsequent cardiac hypertrophy." (PMID 35030174, 2022). "At the sarcomeric level, titin plays a key role in the mechanotransductive response of the cardiomyocyte and regulation of cardiac hypertrophy." (PMID 29073955, 2017). "Defects in a large set of sarcomeric proteins such as cardiac β myosin heavy chain, α-tropomyosin, titin, and cardiac α-actin have been demonstrated to induce cardiac hypertrophy." (PMID 18682726, 2008). "FHL1 was also found to be upregulated in a titin PEVK knockout mouse model that developed cardiac hypertrophy and increased passive tension, strengthening the importance for an interaction between titin’s molecular spring elements and FHL1 during regulation of LV passive/diastolic tension." (PMID 34745373, 2021). "While PKD ablation in cardiomyocytes appears to be protective against pressure overload-induced cardiac hypertrophy and fibrosis, to what extent such an effect is due to TTN hypophosphorylation remains unclear as the contribution from other PDK substrates cannot be completely ruled out." (PMID 34445638, 2021). "Thus, the reversion of diastolic dysfunction and cardiac atrophy in N2B-KO mice by reduced expression of functional RBM20 is dependent on titin’s mechanical properties and associated with a posttranscriptional effect on FHL1, which links titin-based biomechanics to cardiac hypertrophy signaling." (PMID 27889803, 2016). "For the first time, we demonstrated that myocardial hypertrophy induced by a UUO of several weeks’ duration is accompanied by electrophysiological remodeling and increased titin content." (PMID 40869420, 2025). "Lactic acid, a signaling molecule mediating various pathological and physiological processes, has been shown in recent studies to potentially regulate myocardial hypertrophy by restoring the lactylation of α-MHC and its interaction with titin." (PMID 40166465, 2025). "Recent studies suggest that administering lactic acid or inhibiting its efflux may regulate myocardial hypertrophy by restoring the lactylation of α-MHC and the interaction between α-MHC and titin." (PMID 40166465, 2025).
cardiac hypertrophy (continued). "UUO resulted in cardiac hypertrophy, accompanied by an elongation of the QRS wave on the ECG, decreased expression of Cxcl1, Cxcl9, and Il1b, reduced the number of CD11b+ cells, and increased in titin isoform parameters, such as T1/MHC and TT/MHC ratios, without changes in fibrosis markers." (PMID 40869420, 2025).
atrial fibrillation (17 papers, 2017 to 2026). A disorder characterized by an electrocardiographic finding of a supraventricular arrhythmia characterized by the replacement of consistent P waves by rapid oscillations or fibrillatory waves that vary in size, shape and timing and are accompanied by an irregular ventricular response. "Atrial fibrillation (ICD10 code I48) was associated with rare variation in 8 genes (TTN, RPL3L, KLF1, TET2, NME3, KDM5B, PKP2, PMVK)." (PMID 38390584, 2024). "Atrial fibrillation was associated with rare variations in 8 genes (TTN, RPL3L, KLF1, TET2, NME3, KDM5B, PKP2, PMVK)." (PMID 38390584, 2024). "Four of these genes have previously been linked in GWAS to atrial fibrillation (TTN, RPL3L, PKP2, PMVK)." (PMID 38390584, 2024). "Although the PVs in the TTN gene have been associated with atrial fibrillation and ventricular arrhythmias, the role of the TTN gene in intraventricular conduction defect, namely LBBB, is unclear." (PMID 34790974, 2021). "We perform whole-exome sequencing on 24 families with at least three family members diagnosed with atrial fibrillation (AF) and find that titin-truncating variants (TTNtv) are significantly enriched in these patients (P = 1.76 × 10−6)." (PMID 30333491, 2018). "Finally, we also identified heterozygous missense variants in the TTN gene in patients with cardiac conduction and rhythm disorders, including atrial flutter, atrial fibrillation, supraventricular tachycardia, atrioventricular block, bradycardia, and Ebstein’s anomaly." (PMID 41465321, 2025). "Furthermore, GWAS of multiple cardiac traits, such as atrial fibrillation and PR interval, identified loci associated with embryonic development-associated genes and genes whose mutations are known to cause serious heart defects, such as TTN, GATA4, MYH6, NKX2-5, PITX2, and TBX52–4." (PMID 36854752, 2023). "Novel variants in DCTN1, MYH14, and RBM20 were identified in Family 1 with cardiac and limb-girdle muscle involvement and in TRIM63, ACTC1, and TTN in the proband of family 2 with a distal lower limb phenotype and atrial fibrillation." (PMID 33170376, 2021). "In addition to their role in DCM, causative variants in the TTN gene have also been associated with HCM, RCM, ARVC, and, most importantly, atrial fibrillation." (PMID 40207042, 2025). "The first reported association between TTN and arrhythmias at the ion level was in atrial fibrillation, where a nine-amino acid deletion within the A-band Ig-like domain of titin resulted in a gain-of-function of slow delayed rectifier potassium current as well as a shortened APD." (PMID 41552678, 2025). "Interestingly, Fhl2 had one of the highest fold-changes in expression in the left atria of patients with atrial fibrillation compared to healthy controls, supporting a role for dysregulated TTN signaling in the pathobiology of atrial fibrillation." (PMID 28720711, 2017).
gastric cancer (17 papers, 2017 to 2025). A primary or metastatic malignant neoplasm involving the stomach. "In some literatures, MUC16 mutation is associated with better prognosis and higher TMB in gastric cancer, while TTN mutation is associated with immune checkpoint blockade in solid tumors." (PMID 37274740, 2023). "Additionally, Yang and his colleagues found that MUC4, MUC16, and TTN mutations were associated with the immune prognosis of gastric cancer in the immunotherapy cohort." (PMID 34513703, 2021). "TTN is responsible for encoding a transmembrane protein present in striated muscle tissues, in addition to being studied in different populations, being correlated with poor prognosis for Gastric Cancer in Chinese, and the most prominently related to various cancers, found in about 56% of tumors." (PMID 37763132, 2023). "A significant portion of 16 new variants were found in the TTN gene, including the two high-impact variants, and the other new variant, the INDEL type, was found in the CDH1 gene, which is highly associated with the development of Gastric Cancer." (PMID 37763132, 2023). "Building upon this observation, it is worth highlighting that prior research has unequivocally established the significance of TTN and MUC16 gene mutations in shaping the prognosis of gastric cancer, while also serving as pivotal biomarkers for guiding the administration of ICIs." (PMID 38066437, 2023). "Besides, the combined mutation status of MUC4, MUC16, and TTN showed the potential to predict TMB and immunotherapy efficacy in gastric cancer and pan cancer." (PMID 37814942, 2023). "In the present study, we analyzed the DNA sequencing data of 229 patients from the TCGA-STAD project and identified five potential driver genes (CCDC169-SOHLH2, TTN, KNL1, C6, NRXN1) whose mutations were negatively associated with gastric cancer recurrence (p < 0.01)." (PMID 35187167, 2022). "Despite reports suggesting that a TTN (titin) mutation plays an important role in immunotherapy of solid tumors and gastric cancer, the relationship between the TTN mutation and LUAD immunotherapy has not been determined." (PMID 34513703, 2021). "As for TTN and MUC16, the study of gastric cancer or ferroptosis is still blank." (PMID 34977116, 2021).
lung adenocarcinoma (17 papers, 2016 to 2025). A carcinoma that arises from the lung and is characterized by the presence of malignant glandular epithelial cells. "Previous studies have indeed shown that TTN mutations are associated with high immunogenicity and an inflammatory tumor immune microenvironment in lung adenocarcinoma." (PMID 39669362, 2024). "Our data showed that the gene heterogeneity expression, which was driven by TTN mutations, prolonged the survival of lung adenocarcinoma patients and provided valuable clues for the prognosis of TTN gene mutations in lung adenocarcinoma." (PMID 37035196, 2023). "In this study, the Cancer Genome Atlas (TCGA) dataset was used to analyze the TTN mutations in lung adenocarcinoma." (PMID 37035196, 2023). "TTN is another frequently mutated gene in a variety of human cancers, such as lung adenocarcinoma, lung squamous cell carcinoma and colon adenocarcinoma." (PMID 36805828, 2023). "Previous studies show that TTN mutation is related to high immunogenicity and inflammatory tumor immune microenvironment in lung adenocarcinoma, accompanied by favorable objective response and survival with ICI administration." (PMID 37055842, 2023). "The incidence of TTN mutations in lung adenocarcinoma was found to be 73%, and it was related to the prognosis of lung adenocarcinoma." (PMID 37035196, 2023). "More encouragingly, deep learning techniques have raised many opportunities to discover and identify drugs sensitive to human cancers, such as cimetidine sensitive to lung adenocarcinoma, emetine to atypical meningiomas, and vinorelbine to TTN-mutated tumors." (PMID 36532083, 2022). "TTN mutation status can independently predict immunotherapy prognosis in lung adenocarcinoma patients after ICIs." (PMID 34970479, 2021). "Additionally, TTN mutation has been linked to high immunogenicity and inflammatory tumor immune microenvironment, indicating that TTN mutation may serve as a potential predictive marker for lung adenocarcinoma patients who may benefit from ICIs." (PMID 37021811, 2023). "We found that the mutation rates of TTN, PCLO, RYR3, and LRP2 in human lung adenocarcinoma were 41%, 16%, 14% and 11%, respectively, but the mutation rates of other mutant genes were <10%." (PMID 34858801, 2021). "Our result suggested that mutations of TTN, MUC16 and CSMD3 may be associated with low expression of LINC02126 in lung adenocarcinoma." (PMID 36357869, 2022). "Furthermore, downregulation of titin expression using titin-antisense RNA1 (titin-AS1) positively correlated with more advanced disease and poorer prognosis, such as tumor size, tissue invasion, and advanced stage in lung adenocarcinoma." (PMID 39944242, 2025).
colon cancer (16 papers, 2017 to 2025). "TTN mutations have recently been reported in triple negative breast cancer and colon cancer, although therapeutic implications are unknown." (PMID 28423512, 2017). "Manipulating the expression of TTN in tumour cells revealed the positive impact of TTN overexpression on colon cancer cells in terms of the proliferation, invasion and metastasis, proving the involvement of TTN in colon cancer progression." (PMID 37499109, 2023). "Furthermore, GSEA was used to analyse the possible mechanisms of TTN‐induced colon cancer and found that the ERB pathway was associated with TTN in colon cancer based on bioinformatics analysis." (PMID 37499109, 2023). "According to the results in the study, TTN may remarkably impact colon cancer process through the ERB pathway and high expression of TTN indicates a poor prognosis of colon cancer patients." (PMID 37499109, 2023). "Consequently, our findings suggest that the absence of TTN in mouse colon cancer cells inhibits tumour growth in vivo." (PMID 39748197, 2025).
myositis (16 papers, 2016 to 2025). "Consequently, further evidence is warranted that titin-Ab and, particularly, RyR-Ab may be associated with MG-myositis cases." (PMID 27623618, 2016). "In cases where myasthenia and myositis overlap, anti-striational antibodies including titin, ryanodine receptor, muscular voltage-gated potassium channel, Kv1.4 were detected in approximately 75% patients." (PMID 36568231, 2022). "In particular, we suggest that myositis/MG -Ab investigations should include titin-Ab and RyR-Ab screening." (PMID 27623618, 2016).
arrhythmogenic right ventricular cardiomyopathy (14 papers, 2013 to 2025). "Furthermore, TTN mutations have been implicated in arrhythmogenic right ventricular cardiomyopathy (ARVC), a distinct clinical entity with characteristic features and outcomes." (PMID 41190030, 2025). "Furthermore, TTN mutations can also cause arrhythmogenic right ventricular cardiomyopathy (ARVC) with distinct clinical features and outcomes." (PMID 27493940, 2016). "There is very limited data on possible consequences of disruptions in FN3 elements within the conserved titin A-band region, although there has been a report of a mutation occurring within FN3 domains in patients with arrhythmogenic right ventricular cardiomyopathy." (PMID 23514108, 2013). "It was previously reported that mutations in the TTN gene have been related to different forms of cardiomyopathy, including HCM, DCM, and arrhythmogenic right ventricular cardiomyopathy (ARVC)." (PMID 32178433, 2020).
centronuclear myopathy (14 papers, 2014 to 2025). Centronuclear myopathy (CNM) is an inherited neuromuscular disorder characterized by clinical features of a congenital myopathy and centrally placed nuclei on muscle biopsy. "Recent studies demonstrate that truncating TTN mutations promote the development of congenital myopathies in centronuclear myopathies (CNM)." (PMID 40264452, 2025). "The winning team also cited a conference abstract, then available on the web and now published, describing a parallel study of a cohort of patients with centronuclear myopathy with validated mutations in the TTN gene." (PMID 24667040, 2014).
colorectal cancer (14 papers, 2018 to 2025). A primary or metastatic malignant neoplasm that affects the colon or rectum. "On the other hand, TTN mutations have been associated with poor immune infiltration and worse prognosis in liver hepatocellular carcinoma, colorectal cancer, and ovarian serous cystadenocarcinoma." (PMID 40692788, 2025). "In colorectal cancer, TTN was identified as the most frequently mutated gene within the pan-cancer cohort, and its mutation number showed the best correlation with TMB." (PMID 35402275, 2022). "Within these pleiotropic genes, MXR5 was associated with colorectal cancer; TRPM1 and UCKL1 were linked to prostate cancer, and TTN was associated with both cancer types." (PMID 41234971, 2025). "Mutations of the APC, TTN, MUC16, and KRAS genes were high in frequency in both colorectal adenoma and colorectal cancer samples." (PMID 37546388, 2023). "ADAMTS20 was found to be downregulated in colorectal cancer and TTN was reported to be frequently detected in solid tumors including colorectal cancer." (PMID 35402275, 2022). "For the dataset of all mutations, the cancer type-specific six gene mutation biomarkers were APC for colorectal cancer, PTEN for endometrial cancer, BRAF for thyroid cancer and MUC16, DNAH5, TTN for cutaneous melanoma." (PMID 30662873, 2018). "In colorectal cancer, a significant decrease in titin expression has been demonstrated." (PMID 39944242, 2025). "In addition to these commonly mutated genes, genomic mutations in SYNE1, TTN, NEB, and CCDC168 were found to be associated with a poor prognosis of colorectal cancer in this study." (PMID 35975176, 2022). "Previous studies have also found that overexpression of titin in colorectal cancer (CRC) cells promotes proliferation and metastasis, and that a lower survival rate was noticeably correlated with a higher titin expression level in CRC tumors." (PMID 39337369, 2024).